GSTP1 (glutathione S-transferase pi 1)
Diseases named in the same sentence as GSTP1 in open-access papers (continued):
Sharing a sentence is not in itself a finding about the gene and the disease.
ovarian tumors (4 papers, 2013 to 2021). "Interestingly, the response rate to chemotherapy for GSTP1-positive ovarian tumors was significantly lower than the GSTP1-negative tumors in a different cohort." (PMID 33946704, 2021). "Ovarian tumors express conjugation phase enzymes as well; moreover, the GST class-pi (GSTP1) enzyme has been reported as one of the most abundantly expressed genes in ovarian tumors, whereas the sulfotransferase SULT1E1 as an independent positive prognostic factor in HGSOC." (PMID 34638494, 2021). "Similarly, an independent epidemiological study identified a drug-resistant phenotype in GSTP1-expressing ovarian tumors in Japanese women." (PMID 33946704, 2021). "Aberrant methylation of GSTP1 and MGMT were exclusively demonstrated in invasive ovarian carcinomas, differentiating between ovarian tumors with low malignant potential and invasive ovarian tumors." (PMID 24086249, 2013).
pancreatic ductal adenocarcinoma (4 papers, 2020 to 2025). An infiltrating adenocarcinoma that arises from the epithelial cells of the pancreas. "This study investigates GSTP1 as a therapeutic target for pancreatic ductal adenocarcinoma (PDAC) using inducible knockdown models." (PMID 40719618, 2025). "Silencing of GSTP1 in pancreatic ductal adenocarcinoma cells can affect both proliferation and apoptosis." (PMID 35936694, 2022).
psoriasis (4 papers, 2015 to 2024). An autoimmune condition characterized by red, well-delineated plaques with silvery scales that are usually on the extensor surfaces and scalp. "On the other hand, GSTP1 was significantly higher in supernatants extracted from donors with psoriasis than in those from donors with dermatitis [FC = 2.4; p = 0.03] or lichen [FC = 3.4; p = 0.03]." (PMID 39062477, 2024). "The list of differentially expressed proteins also includes immune-related molecules, such as in TPM4 [FC = 2.2; p = 0.009], Serglycin (SRGN) [FC = 0.08; p = 0.03] or antioxidant proteins, such as GSTP1 [FC = 5.3; p = 0.03] in psoriasis." (PMID 39062477, 2024). "Oxidative damage has now been implicated in various skin disorders, including premature aging, psoriasis, and atopic dermatitis and if oxidative stress increases GSTP1/2 expression it may explain the decrease in glutathione in these conditions." (PMID 34632319, 2021). "The proteins identified by LC–MS/MS, including SFN, GSTP1, FABP5, S100A7, and RABP2, were also observed to be upregulated in psoriasis lesional tissues." (PMID 32817748, 2020). "Using two-dimensional (2D) gel electrophoresis, an early study identified 21 skin proteins, including eight proteins with 2-fold increased abundance in psoriasis lesions (SERPINB4, GSTP1, SERPINB5, ARHGDIA, HSPB1, KRT14, KRT17, YWHAQ) and two others with 2-fold decreased abundance (KRT15, CALR)." (PMID 26251673, 2015).
renal cell carcinoma (4 papers, 2013 to 2025). "Characteristics of the included case-control studies in the meta-analysis of the association between GSTP1 polymorphism and the risk of renal cell carcinoma." (PMID 23717494, 2013). "We performed a quantitative meta-analysis to assess the possible associations between the GSTM1, GSTT1 and GSTP1 genotypes and their individual susceptibilities to renal cell carcinoma." (PMID 23717494, 2013). "Association of GSTM1- and GSTT1-null genotypes, GSTP1 A/G gene polymorphism with renal cell carcinoma (RCC) susceptibility was detected, and the relationship between the GSTM1/GSTT1-null genotype and clinical TNM stages of RCC was assessed, using meta-analysis method." (PMID 29884137, 2018). "GSTP1-1 is generally present in renal cell carcinoma; however, the level of expression has been reported to be increased, unchanged or decreased compared with normal kidney tissue." (PMID 31357662, 2019). "The renal cell carcinoma and transitional cell carcinoma of the urinary bladder studies offered experimental data to determine if the GSTP1-1 may be considered a potential urinary marker." (PMID 31357662, 2019). "The association of the three Glutathione S-transferases (GSTs) polymorphisms (GSTM1, GSTT1 and GSTP1) genotypes with their individual susceptibilities to renal cell carcinoma (RCC) has not been well established." (PMID 23717494, 2013).
transitional cell carcinoma of urinary bladder (4 papers, 2010 to 2023). "Plasma GSTP1-1 could be considered as a marker of transitional cell carcinoma of the urinary bladder, in fact, elevated levels of GSTP1-1 were found in patients with tumors." (PMID 31357662, 2019). "GSTP1-1 overexpression is characteristic of transitional cell carcinoma of the urinary bladder." (PMID 31357662, 2019).
acute lymphoblastic leukemia (3 papers, 2015 to 2018). Leukemia with an acute onset, characterized by the presence of lymphoblasts in the bone marrow and the peripheral blood. "For example, GSTP1 rs1695 was reported to be associated with the risk of esophageal cancer and malignant melanoma in the Caucasian population, but not childhood acute lymphoblastic leukemia (ALL) or bladder cancer." (PMID 30740061, 2018). "The authors suggested that GSTM1 and GSTT1, but not GSTP1 polymorphisms, were associated with a modest increase in the risk of acute lymphoblastic leukemia and GSTM1/GSTT1 null genotypes could play a role in leukemogenesis." (PMID 28902850, 2017).
alcoholic liver damage (3 papers, 2022). "Glutathione detoxification enzyme genes, including Gsta1, Gstm3, Gstm1, Gstp1, Gclm, and Gclc, play important roles in protecting against alcoholic liver damage and diseases." (PMID 36359319, 2022). "Glutathione detoxification enzymes including Gsta1, Gstm3, Gstm1, Gstp1, Gclm, and Gclc play important roles in protecting against alcoholic liver damage and diseases." (PMID 35565941, 2022). "In addition, ginseng Huang jiu could improve alcoholic liver disease by regulating the GSTP1, HRAS, AKR1B1, GSTA1, Androgen receptor (AR), GSR, and LDHB genes through bioinformatics analysis." (PMID 36034901, 2022).
allergic disease (3 papers, 2008 to 2016). An immune response that occurs following re-exposure to an innocuous antigen, and that requires the presence of existing antibodies against that antigen. "The effect of air pollution from traffic on childhood allergy appears to be modified by GSTP1 and TNF variants, supporting a role of genes controlling the antioxidative system and inflammatory response in allergy." (PMID 18709160, 2008). "Nevertheless, lack of association of GSTP1-1 polymorphisms with allergic diseases or drug hypersensitivity has been reported in other studies, potentially due to differences in the genetic backgrounds of the patient cohorts studied." (PMID 27540362, 2016). "Moreover, GSTP1-1 emerges as a key factor to be considered in future genomic studies related with allergy development and drug hypersensitivity reactions." (PMID 27540362, 2016). "Our goal was to assess interactions between exposure to air pollution and single nucleotide polymorphisms (SNPs) in the β2-adrenergic receptor (ADRB2), glutathione S-transferase P1 (GSTP1), and tumor necrosis factor (TNF) genes for development of childhood allergic disease." (PMID 18709160, 2008).
Anxiety (3 papers, 2014 to 2025). Intense feelings of nervousness, tension, or panic often arise in response to interpersonal stresses. "Melatonin has also been reported to it could lessen anxiety and depression‐like behaviors of AD mice by regulating the expression of glutathione S‐transferase P1 (GSTP1) and complexin‐1 (CPLX1) in the hippocampus." (PMID 39056330, 2024). "Then, in 2017, a study reported that GSTP1 was involved in anxiety and depression behaviors in 10-month-old triple transgenic mice of AD, and melatonin could serve as a potential candidate drug to improve the neuropsychiatric behaviors in AD via modulating the expression of the GSTP1." (PMID 40186323, 2025).
astrocytoma (3 papers, 2015 to 2025). "Lastly, the comparison among astrocytomas and adenocarcinomas only revealed a significant difference for GSTP1 (UGSTP1 = 8, p = 0.007, r = -0.57)." (PMID 26580399, 2015). "A correlation between the gene expression and the protein product was observed for AOX1, GSTP1 and GSTM3 in astrocytomas." (PMID 26580399, 2015).
atopic dermatitis (3 papers, 2011 to 2024). "The genetic polymorphisms in GSTM1 and GSTP1 may be responsible for differences in susceptibility to atopic dermatitis with regard to prenatal smoke exposure." (PMID 21838884, 2011).
autism (3 papers, 2011 to 2025). Persistent deficits in social interaction and communication and interaction as well as a markedly restricted repertoire of activity and interest as well as repetitive patterns of behavior. "Polymorphisms in glutathione S-transferase mu 1 (GSTM1), glutathione S-transferase pi 1 (GSTP1), and glutathione peroxidase 1 (GPX1), which modulate the response to oxidative stress, have been associated with increased autism risk." (PMID 21156395, 2011).
Autoimmunity (3 papers, 2013 to 2022). The occurrence of an immune reaction against the organism's own cells or tissues. "In addition, besides MNRR1, a number of other nDNA-encoded mitochondrial proteins such as GSTP1, PINK1, SPATA5 and MFF have been implicated in BC progression or BC risk, suggesting that mitochondrial autoimmunity prominently participates in breast carcinogenesis." (PMID 33615312, 2020).
brain tumors (3 papers, 2015 to 2021). "In the case of cisplatin, the therapeutic efficiency of brain tumor treatment can be increased by using ezatiostat, an inhibitor of GSTP1." (PMID 34065991, 2021). "Therefore, cisplatin chemotherapy using an inhibitor of GSTP1 can enhance the therapeutic efficiency in brain tumors." (PMID 34065991, 2021). "GSTP1 is the primary isoenzyme contributing to total GST activity in both normal brain and brain tumors." (PMID 26580399, 2015). "GSTP1 also suppresses JNK downstream signaling and apoptosis in brain tumor cells." (PMID 31024008, 2019).
colorectal adenocarcinoma (3 papers, 2005 to 2024). The most common type of colorectal carcinoma. "We found significantly higher expression of thymidylate synthase (TYMS) and GSTP1 in mucinous colorectal adenocarcinomas than in equivalent-stage nonmucinous tumours." (PMID 15655543, 2005).
coronary artery disease (3 papers, 2020 to 2023). "However, among the Indian population of South Africa, a correlation between the GSTM1-null genotype and the A105 allele of GSTP1 and ischemic heart disease was found." (PMID 37819495, 2023). "There are meta-analyses demonstrating that GSTM1 null, GSTP1 null and GSTT1 null polymorphisms were significantly associated with an increased risk of coronary artery disease (CAD) in overall population." (PMID 37819495, 2023). "On the other hand, studies on the Taiwanese population did not reveal that the GSTM1, GSTT1, GSTP1 and GSTA1 polymorphisms were associated with ischemic heart disease." (PMID 37819495, 2023). "Whether glutathione S-transferase (GST) null polymorphisms, namely GSTM1 null, GSTP1 null and GSTT1 null polymorphisms, influence the risk of coronary artery disease (CAD) or not remains unclear." (PMID 32905149, 2020).
dermatitis (3 papers, 2021 to 2024). An inflammatory process affecting the skin. "Unexpectedly, a significant relationship between dermatitis and the levels of certain insulin-biosynthesis-and-secretion- or insulin-resistance-related polypeptides (GSTO1, FETUA, GSTP1, IGFALS or LDHA) was observed." (PMID 39062477, 2024).
diabetic cardiomyopathy (3 papers, 2024 to 2025). Diabetic cardiomyopathy is a disorder of the heart muscle in people with diabetes. "Adding further evidence to this cardiometabolic link, the authors of that study demonstrated that SIRT5-mediated lysine demalonylation of GSTP1 protects cardiomyocytes from pyroptosis in diabetic cardiomyopathy." (PMID 41107644, 2025).
diabetic nephropathy (3 papers, 2023 to 2024). "The present study was designed to investigate the possible modifying effect of glutathione transferase polymorphisms (GSTM1, GSTT1, GSTP1 rs1138272/rs1695, GSTO1 rs4925 and GSTO2 rs156697) in the susceptibility to T2DM and diabetic nephropathy." (PMID 36676788, 2023). "Hence, the present study was designed to investigate the possible modifying effect of GSTs polymorphisms (GSTM1, GSTT1, GSTP1, GSTO1 and GSTO2) in the susceptibility to T2DM and diabetic nephropathy as its major microvascular complication." (PMID 36676788, 2023).
emphysema (3 papers, 2007 to 2016). "Upper lung-dominant emphysema is associated with genetic variants in MMP-9 or EPHX1 and GSTP1 and the cranial-caudal emphysema distribution is a powerful predictor of the response to lung volume reduction surgery." (PMID 22512922, 2012). "Previous studies have shown that variants of MMP-9 or EPHX1 and GSTP1 are associated with upper-predominant emphysema." (PMID 22512922, 2012). "The significant genotype-phenotype associations for SNPs in GSTP1 and EPHX1 were further evaluated in four clinically-defined subgroups of patients in NETT, based on emphysema distribution and baseline exercise capacity." (PMID 17686149, 2007). "In the NETT Genetics Ancillary Study, we were able to identify variants in two genes, GSTP1 and EPHX1, which may predict outcome from LVRS, even when accounting for clinically-defined subgroups based on radiographic emphysema distribution and baseline exercise capacity." (PMID 17686149, 2007). "Analysis of SNPs in GSTP1 in all subjects (significant at p < 0.05) and in 4 subgroups defined by NETT based on upper lobe predominant emphysema on chest CT (upper lobe predominant vs. non-upper lobe predominant) and baseline exercise capacity (low vs. high)." (PMID 17686149, 2007).
Insulin resistance (3 papers, 2012 to 2025). Increased resistance towards insulin, that is, diminished effectiveness of insulin in reducing blood glucose levels. "Another research on humans showed that participants with Gstp1 AG genotypes showed stronger associations between insulin resistance markers who were exposed to air pollution." (PMID 37033250, 2023). "This study shows that overexpression of the G0S2 gene aggravates liver insulin resistance of mice through upregulating P-Foxo1, Socs3, and Ptpn1 and downregulating Gstp1 and Ppar-γ, which demonstrates that G0S2 may be a potential target gene for the treatment of NAFLD, obesity, and diabetes." (PMID 37033250, 2023).
intraepithelial neoplasia (3 papers, 2010 to 2025). A precancerous neoplastic process that affects the squamous, glandular, or transitional cell epithelium without evidence of invasion. "Hypermethylation of the GSTP1 promoter with reduced expression levels is detected in precursor high-grade intraepithelial neoplasia (HG-PIN)." (PMID 20671914, 2010). "In addition, methylation of KLLN, CHFR, TP73, GSTP1, and CASP8 may be related to precancerous processes, such as epithelial hyperplasia and epithelial dysplasia." (PMID 35681626, 2022).
laryngeal carcinoma (3 papers, 2012 to 2021). Carcinoma that arises from the laryngeal epithelium. "In stable transfection of laryngeal carcinoma, HEp2 cells with human GSTP1 resulted in a 3-fold increase in doxorubicin resistance, compared with that of the control cells." (PMID 33802702, 2021).
liver cirrhosis (3 papers, 2018 to 2023). "Rs1695 has been found in GSTP1 genes, some of which increased the occurrence of liver cirrhosis." (PMID 33291080, 2020). "However, changes in the methylation level of the “driver” genes for oncopathology (АРС, CDKN2B, GSTP1, ELF4, TERT, WT1) are registered in tumor tissue in the setting of liver cirrhosis but not fibrosis." (PMID 36923478, 2023). "However, GSTP1 was not related to HCC patients’ age, gender, hepatitis B surface antigen (HBsAg), liver cirrhosis, Tumor-Node-Metastasis (TNM), portal vein tumor thrombosis (PVTT), or Edmondson-Steiner grade (all P > 0.05)." (PMID 29507666, 2018).
malignant glioma (3 papers, 2013 to 2025). A grade III or grade IV glioma arising from the central nervous system. "In malignant glioma, the expression of GSTP1 protein, the most discussed GST superfamily member, is increased and contributes to TMZ resistance." (PMID 34209254, 2021).
mucinous tumours (3 papers, 2005 to 2018). "Mucinous tumors overexpress also glutathione S-transferase pi 1 (GSTP1) gene encoding enzyme involved in the detoxification of platinum agents by glutathione (GSH) conjugation expecting a weak response to oxaliplatin-treatment." (PMID 29416702, 2018). "The authors found an overexpression of TS and GSTP1 (glutathione S-transferase pi) genes in mucinous tumours." (PMID 19259089, 2009). "As GSTP1 is a major rout of detoxification of platinum agents, one could expect that the overexpression of TS and GSTP1 genes in mucinous tumours may be responsible for decreased clinical response to treatment with 5-FU and OXA." (PMID 19259089, 2009). "GSTP1 expression was also significantly greater in mucinous tumours (193.0 [108.8, 277.3]) than in nonmucinous tumours (139.0 [72.2, 205.8], P=0.029)." (PMID 15655543, 2005). "In conclusion, mucinous tumours significantly overexpressed TYMS and GSTP1 relative to both normal mucosa and to nonmucinous adenocarcinomas." (PMID 15655543, 2005).
polyneuropathy (3 papers, 2019 to 2024). A disease or disorder affecting more than one nerve. "The GSTP1 rs1695 AG genotype was previously associated (~4 fold) with the clinical signs of polyneuropathy in adults of the same ethnicity." (PMID 38922121, 2024). "This is in agreement with studies that report that G allele of GSTP1 rs1695 has been associated with an increased risk of myelosuppression, polyneuropathy, and toxicity." (PMID 30914949, 2019). "For the somatosensory signs, individuals carrying the GSTP1 AG genotype had an approximately 4-fold higher chance of having clinical signs of polyneuropathy, while the other signs were not significant among different GSTP1 genotypes." (PMID 36851015, 2023).
proliferative inflammatory atrophy (3 papers, 2013 to 2015). A lesion in the prostate gland characterized by glandular atrophy, chronic inflammation, and epithelial hyperplasia. "It has also been detected in proliferative inflammatory atrophy (PIA) lesions, although the mechanism by which GSTP1 subsequently alters methylation and silences transcription during progression from PIA to PIN remains to be elucidated." (PMID 25738352, 2015).
rectal cancer (3 papers, 2014 to 2025). A primary or metastatic malignant neoplasm that affects the rectum. "Heterozygous genotypes were significantly linked to increased risks of both colon and rectal cancer (P < 0.05) for GSTP1(rs1695, rs1138272) and PTEN (rs701848)." (PMID 39754630, 2025). "In addition, the GSTP1 rs1138272 polymorphism together with the GSTM1 (glutathione S-transferase M1) null genotype was reported to be associated with the risk of colon or rectal cancer in the Indian population." (PMID 30740061, 2018). "The study analyzed CRC patients based on tumor location to assess the association of the GSTP1 and PTEN polymorphism and the link between the these polymorphisms and CRC was evaluated by sub-grouping the patients into those with colon and rectum cancers." (PMID 39754630, 2025).
skin cancer (3 papers, 2005 to 2025). "The aim of this study was to investigate the role of GSTP1 and MRPs in resistance of this skin tumour to drugs." (PMID 15999103, 2005).
testicular cancer (3 papers, 1993 to 2020). A primary or metastatic malignant neoplasm that affects the testis. "For example, in a study involving 173 survivors of testicular cancer, genetic variants of glutathione S-transferase (GST) are described as a key determinant of cisplatin-induced ototoxicity: the GSTM1 polymorphism is described as detrimental and 105Val-GSTP1 described as protective." (PMID 22919381, 2012).